RN7SL600P (RNA, 7SL, cytoplasmic 600, pseudogene)
Gene: Miscellaneous RNA gene on chromosome 1 (150,568,971 to 150,569,269, reverse strand). Ensembl gene ENSG00000274963.
Homologues: Orthologues: chimpanzee Metazoa_SRP (99% identical), macaque Metazoa_SRP (95% identical). Paralogues in human: RN7SL473P (93% identical), RN7SL1 (82% identical), RN7SL3 (82% identical), RN7SL2 (81% identical), RN7SL679P (80% identical), RN7SL45P (80% identical), RN7SL481P (79% identical), RN7SL786P (79% identical), RN7SL464P (79% identical), RN7SL607P (79% identical), RN7SL664P (79% identical), RN7SL709P (79% identical), and 700 more.